PRL (prolactin)
Diseases named in the same sentence as PRL in open-access papers (continued):
Sharing a sentence is not in itself a finding about the gene and the disease.
adenoma (continued). "The majority of adenomas found in the Aip mouse model were somatotropinomas, although mixed GH/prolactin, prolactinomas, and ACTH-corticotropinomas were also found." (PMID 25136513, 2014). "In summary, PRL-secreting adenomas, especially macroadenomas, have larger diameters and perimeters than nonfunctioning and GH-secreting adenomas." (PMID 25431591, 2014). "Like PRL-secreting adenomas, circulating levels of PRL are elevated in diabetes; accordingly, they are higher in diabetes patients without retinopathy than in those with proliferative diabetic retinopathy, which is an angiogenic disease." (PMID 25431591, 2014). "In the setting of simultaneous excessive growth hormone (GH) and prolactin secretion, the two hormones are most often secreted by the same adenoma." (PMID 25298881, 2014). "The expression of Notch3 was moderately elevated in NFPAs compared with functional adenomas, which included GH- and PRL-secreting adenomas." (PMID 23426998, 2013). "Unlike RT-PCR analysis, Notch3 protein expression was significantly elevated in NFPAs compared with functioning adenomas (n=9, with 5 GH-secreting adenomas and 4 PRL-secreting adenomas; P=0.002)." (PMID 23426998, 2013). "Notch3 protein expression levels of GH- and PRL-secreting adenomas were similar to those of normal pituitary tissue (n=5, P>0.05; n=4, P>0.05, respectively)." (PMID 23426998, 2013). "We should note that the hormonal analysis showed higher mean PRL serum levels in naïve patients (F = 4.79, p = 0.038), but this was due to the inclusion of patients with mixed GH/PRL secreting adenoma." (PMID 23593161, 2013). "Our data demonstrated paralleled expression of Notch3 between PRL-secreting adenomas and normal controls." (PMID 23426998, 2013). "PRL-secreting adenomas (n=4) demonstrated a 3.9-fold increase in Jagged1 mRNA expression compared with normal pituitary tissue, although the difference was not statistically significant (P=0.204)." (PMID 23426998, 2013). "The girl was successfully treated over years with pamidronic acid to inhibit progressive fibrosis and cabergoline as a prolactin antagonist effective against the adenoma." (PMID 22273876, 2012). "The most commonly reported plurihormonal adenomas coexpress growth hormone (GH), prolactin (PRL), and/or thyroid stimulating hormone (TSH) or luteinizing hormone (LH) and follicle-stimulating (FSH)." (PMID 23320206, 2012). "An excess of growth hormone and prolactin is, in most cases, due to the diffuse hyperfunction of the anterior pituitary lobe, but sometimes adenomas are found." (PMID 22273876, 2012). "These include dimorphic adenomas with GH and prolactin cells, monomorphic mammosomatotroph adenomas, and more primitive acidophilic cell adenomas." (PMID 22518126, 2012). "Only 1 of 17 GH/PRL-secreting adenomas (6%) expressed high clusterin levels, 3 expressed moderate levels, while this protein was minimally detectable in 13 such adenomas." (PMID 21464964, 2011). "Three different adenoma types (GH-, PRL- and gonadotroph) were each analyzed for co-localization of clusterin with respective pituitary hormone markers." (PMID 21464964, 2011). "Prolactin concentrations were not high enough to suggest a macroprolactinoma in the present study, although positive prolactin immunostaining was evident within the adenoma cells’ cytoplasm." (PMID 22011738, 2011). "A rough correlation is evident between prolactin secreting adenoma size and prolactin concentrations." (PMID 22011738, 2011). "It is shorter for PRL-secreting adenomas, which tend to produce systemic metastases more often, whereas ACTH-secreting PCs more commonly produce CNS metastases." (PMID 20806088, 2010). "They show a predilection for GH/PRL-synthesizing adenomas, younger age of onset, and higher penetrance of disease compared to AIP-negative FIPA families." (PMID 20506337, 2010). "When the serum prolactin exceeds 1000 iu/L, a prolactin secreting adenoma needs to be confirmed by appropriate scanning techniques." (PMID 21274298, 2009).
adenoma (continued). "Prolactin secreting adenomas are the most commonly encountered pituitary tumours in women of child bearing age." (PMID 20062694, 2009). "About two-thirds oversecrete pituitary hormones, among which growth hormone (GH) and prolactin (PRL)-oversecreting adenomas are the most common." (PMID 17242703, 2007). "Additionally, the mean age of ACTH-cell adenomas was significantly younger compared to patients with PRL-cell adenomas (12 vs. 15.7 years, p = 0.0031)." (PMID 41571926, 2026). "About 30% of TSHomas are multisecretory Pit-1 adenomas (TSH with PRL and/or GH)." (PMID 40259920, 2025). "Immunohistochemical findings suggest that most of these adenomas are prolactin-secreting." (PMID 41048428, 2025). "PRL levels can be influenced by various factors; higher PRL levels may not only indicate cavernous sinus invasion but also simply reflect adenoma size, adding complexity to the interpretation of results." (PMID 40113928, 2025). "Most functioning adenomas secrete either PRL, GH, or ACTH, in decreasing order of frequency." (PMID 40808829, 2025). "However, our analysis further demonstrated that recovery of hypogonadism is influenced not only by the degree of prolactin normalization but also by initial adenoma size." (PMID 40035956, 2025). "The CPZ gene produces significant immunohistochemical (IHC) staining in the tissues of adrenocorticotropic hormone-synthesizing suprarenal cortical cell adenomas, adenomas of growth hormone (GH)-producing GH cells, and adenomas of prolactin-producing lactation cells." (PMID 41001032, 2025). "Moreover, the efficacy of cabergoline as a treatment for CD is usually low, although an excellent response with recovery of eucortisolism has been reported in a case of PRL/ACTH co-secreting adenoma." (PMID 41201503, 2025). "Patients with non-invasive, small adenomas who exhibit normal serum prolactin levels and significant tumor shrinkage after at least two years of low-dose cabergoline treatment (0.25–0.50 mg per week) have the highest likelihood of maintaining remission following withdrawal." (PMID 41199869, 2025). "Medical therapy with dopamine agonists (DA), mainly with cabergoline, has been historically considered the first line therapy since it is an effective option, resulting in normalization of prolactin serum levels, adenoma shrinkage and gonadal function restoration." (PMID 40995599, 2025). "Patients with baseline prolactin levels below 10638.2 mIU/L (500 ng/mL) had a significantly higher likelihood of achieving normalized prolactin levels and adenoma disappearance than those with prolactin levels exceeding 10638.2 mIU/L (500 ng/mL) (33.8% vs. 12.9%, P = 0.03)." (PMID 41199869, 2025). "Additionally, a positive correlation was found between adenoma size and BMI and HbA1c, adenoma volume and BMI, as well as prolactin with heart rate, BMI, and HbA1c." (PMID 38645431, 2024). "There is a comparable proportion between GH/PRL mixed adenomas and pure GH-secreting adenomas." (PMID 39194755, 2024). "However, a negative correlation was observed between the changes in fT4 and the changes in prolactin and adenoma volume." (PMID 38645431, 2024). "Adenomas can be somatotrophs that produce other hormones, such as growth hormone and prolactin." (PMID 39399532, 2024). "The robustness of the approach is examined with an ensemble machine learning approach (a so-called super learner), where the observed differences in prolactin and adenoma size between female and male patients are preserved and the initial sample size is artificially increased tenfold." (PMID 38544490, 2024). "From the various clinical, endocrine, metabolic, and inflammatory markers tested, we found a positive association between adenoma size/volume and a negative association with fT4 values concerning the time needed for prolactin normalization." (PMID 38645431, 2024).
adenoma (continued). "When accounting for statistical imbalances in the number of micro- and macroadenomas in male patients using a data augmentation method (SMOTE), differences in gender-specific prolactin thresholds with respect to adenoma size remained, with male-specific thresholds being significantly higher." (PMID 38544490, 2024). "When correcting for the imbalance in adenoma size in male patients, we derive higher prolactin thresholds for the entire cohort and the male subgroup with 460.9 μg/L (95% credible interval: 216.1–793.3 μg/L) and 1,326.0 μg/L (95% credible interval: 875.4–2,211.9 μg/L), respectively." (PMID 38544490, 2024). "The change in fT4 correlated with changes in prolactin and adenoma volume." (PMID 38645431, 2024). "For non-PRL-secreting adenomas, GTR was achieved in 152 of 235 cases (64.7%)." (PMID 37025271, 2023). "Therefore, the BC rate trend for PRL-secreting adenomas is less likely to reflect the surgeon's surgical skill accurately." (PMID 37025271, 2023). "However, for PRL-secreting adenomas, the operative time in the late period was significantly lower than that in the early period (120 min vs. 159 min, P = 0.008)." (PMID 37025271, 2023). "This suggests that TSH adenomas originate from pituitary stem cells that differentiate into GH, PRL, or TSH cells, which may play a role in the pathogenesis of TSH-secreting PPA." (PMID 38260014, 2023). "A recent multicenter study collected the long-term results in 289 patients and showed tumor growth control in 95% of treated adenomas (5% had tumor progression) at last follow-up (mean 60 months up to 267 months) and normalization of PRL levels in 43% of the patients at 5 years and 54% at 8 years." (PMID 35000899, 2022). "A marked decline in PRL levels and tumor shrinkage may be obtained with very low Cab dose (0.5 mg/week) even in patients bearing very large adenomas and very high PRL levels." (PMID 35000899, 2022). "The most common adenomas diagnosed are prolactin-secreting pituitary adenomas." (PMID 38983521, 2022). "In MP patients, there is usually a positive correlation between PRL levels and adenoma size." (PMID 35000899, 2022). "Some panelists commented that they would recommend measuring prolactin in dilution only in sera from patients with giant adenomas, while others noted that their laboratory routinely tests for deviations from linearity of measured prolactin, using automated assay platforms (data not shown)." (PMID 34283370, 2022). "Both GH-producing adenomas and mixed PRL-GH-producing adenomas have binding sites for dopamine." (PMID 35612842, 2022). "Additionally, patients with GH/PRL-secreting adenomas had a higher rate of IGF-1 normalization (50%), and tumor shrinkage was detected in 62% (13/21) of patients." (PMID 35612842, 2022). "The whole adenoma stained positive for GH and 15 of them (30%) were positive for PRL." (PMID 35612842, 2022). "According to the postoperative histopathological testing, there were 22 null cell adenomas, 12 silent adenomas (including 1 PRL-positive, 1 GH-positive, 1 ATCH-positive, 5 FSH/LH-positive, 2 TSH-positive, and 4 plurihormonal-positive) among non-functioning adenomas." (PMID 35634502, 2022). "Although we don’t have IHC confirmation, patient 2 could be considered as a mammasomatotroph adenoma (GH and PRL secreting adenoma)." (PMID 36157469, 2022). "Moreover, DER was significantly lower in GH-producing adenomas than in PRL-producing adenomas, NF adenomas, and other adenomas (P < 0.001, P < 0.001, and P = 0.001, respectively)." (PMID 33881731, 2021). "Given that the typical reduction of PRL secreting macro-adenoma with CAB is usually close to 60% in DA-sensitive forms, our experience shows promising results and could pave the way for a prospective study in DA-resistant patients." (PMID 34173929, 2021). "When a cut off PRL value of 204 μg/L (4338 mU/L) was used, specificity was calculated as 93.2%, and sensitivity as 89.1% in distinguishing a macro-adenoma from the more common micro-adenoma." (PMID 33963239, 2021).
adenoma (continued). "In the cases presented here, the 4 patients with prolactinomas received maximally tolerated doses of cabergoline ranging from 10.5 to 14 mg a week, although the adenomas continued to progress and PRL levels remained elevated, necessitating additional therapeutic interventions." (PMID 34867776, 2021). "There are a few reports about therapeutic options to restart or increase dopamine agonist medication for prolactin-producing adenomas during the pregnancy itself; however, this option should be carefully considered because dopamine agonists are also risk factors for PA occurrence." (PMID 34039424, 2021). "Among the 12 DPA investigated, the most frequently associated tumour types comprised GH/PRL/TSH and FSH/LH DPAs (cases 5, 6, 10, 12) followed by GH/PRL/TSH adenoma combined with an ACTH adenoma (cases 2, 8, 9) and corticotroph adenoma combined with a FSH/LH lesion (cases 3, 7)." (PMID 34478014, 2021). "However, we found that GH-producing adenomas had lower contrast enhancement than PRL-, ACTH-, and TSH-producing adenomas." (PMID 33881731, 2021). "The ROC curve analysis used to assess the cut-off of PRL threshold that could distinguish between a micro- and macro-adenoma showed a good performance, with area under the curve being 0.976." (PMID 33963239, 2021). "In addition, this study had a limited number of cases of PRL-producing adenomas due to many patients being on drug treatment at the time of referral to our hospital." (PMID 33881731, 2021). "Therefore, combining our data with previous studies we can suggest that a prolactin of > 235 μg/L (> 5000 mU/L) reliably distinguishes a macroprolactinoma from both micro adenoma and from an NFPA1,9." (PMID 33963239, 2021). "High levels of prolactin (PRL) and 24 h urine free cortisol (24 h UFC) were associated with reduced quality of life in patients with prolactinomas and adrenocorticotropic hormone- (ACTH-) secreting adenomas." (PMID 32377185, 2020). "Recently, a case of isolated PRL-secreting adenoma in a 50-year old patient has been reported." (PMID 31877737, 2019). "In prolactinomas, apart from the cystic ones, adenoma size generally corresponds with PRL levels." (PMID 31847209, 2019). "There was a significant correlation between adenoma size and PRL level (p<0.05, r=0.494)." (PMID 30396878, 2019). "However, for prolactinomas (PRL-adenomas) relative to controls, hPRL was downregulated in only spot v1 by 3.4-fold, and not changed in the other spots." (PMID 30210449, 2018). "Strikingly, none of the samples, including 20 growth hormone-secreting, 20 prolactin-secreting, and 20 non-functioning adenomas, carried either USP48 or BRAF mutations." (PMID 30093687, 2018). "These 11 cases were identified as 4 ACTH, 6 GH and 1 PRL adenoma." (PMID 28900805, 2017). "The rate of GH-secreting adenomas was significantly lower (P<0.05) in MEN1-positive than in MEN1-negative patients of the cohort, whereas the rate of prolactin-secreting adenomas was significantly higher in MEN1-mutated than MEN1-negative probands and cohort (P<0.05 and P<0.01, respectively)." (PMID 29036195, 2017). "Besides inhibition of GH secretion, PEG led to a significant inhibition of PRL secretion in the primary cultures of all the three mixed GH/PRL adenomas tested." (PMID 27267119, 2016). "GLI1 expression levels were significantly elevated in ACTH-, GH- and PRL-expressing adenomas (p = 0.026; p = 0.035; p = 0.0059, respectively) whereas null cell adenomas and FSH-expressing tumors showed similar GLI1 expression levels compared to normal adenopituitary lobes." (PMID 27109116, 2016). "Confirmed microadenoma at initial pituitary exploration prompts to the careful inspection of the anterior and lateral surfaces of the gland for a second tumor as more than 50% of small tumors, particularly GH- and PRL-secreting adenomas, present on the surface of the gland." (PMID 26869991, 2016).
adenoma (continued). "Furthermore, dopamine agonists are recommended for adenomas that secrete both GH and prolactin if pharmacotherapy is needed after surgery because both expression pathways are targeted by these agents." (PMID 27517036, 2016). "Somatotrophic and lactotrophic adenomas were confirmed by GH and PRL production, respectively." (PMID 27340409, 2016). "FPAs, commonly refer to monoclonal, originate from adrenocorticotropic hormone (ACTH) cell adenoma, thyrotropin-stimulating hormone (TSH) cell adenoma, growth hormone (GH) cell adenoma, and prolactin (PRL) cell adenoma, whereas the NFPAs commonly originate from gonadotroph cells." (PMID 27303365, 2016). "However, in China, costs for medication are often considered, when patients select methods for the treatment of PRL secreting adenomas." (PMID 25270611, 2015). "After weighing the risk and benefit of surgery, many patients may select surgical treatment for PRL secreting adenomas in China." (PMID 25270611, 2015). "Even for group 1, the number of PRL-secreting adenomas was lower as compared with previous reports." (PMID 26078755, 2015). "PRL-secreting adenomas values were also different for the two groups." (PMID 26078755, 2015). "Resistance to DAs has several different definitions in the literature, including failure to achieve normal PRL levels or adenoma shrinkage of >50 %, failure to reduce PRL by >50 %, or to induce ovulation in women, or failure to reduce symptoms or normalize PRL despite CAB dose ≥2 mg/week." (PMID 28702224, 2015). "Interestingly, ACKR3 was expressed by all the PAs, especially in GH and PRL secreting adenomas and it was observed that its expression was significantly higher in macro- than micro-adenomas." (PMID 26441831, 2015). "This being the first comparative observational cross-sectional study including countries from Southeastern and Eastern Europe, further studies need to develop for elucidation of etiological factors influencing the lower number of PRL-secreting adenomas in these regions." (PMID 26078755, 2015). "Thus, histopathological diagnosis can be extremely challenging in cases of PRL-producing adenomas characterized by remarkable spindle-shaped cells with nuclear pleomorphism, as described in the present study." (PMID 26228535, 2015). "Both PRL and GH secreting adenomas are the most common functioning adenomas." (PMID 25270611, 2015). "Approximately 25% of GH-secreting adenomas co-secrete prolactin." (PMID 25298881, 2014). "In addition, the prolactin-inhibiting mechanism can affect not only adenoma cells but also normal prolactin-secreting cells." (PMID 25142896, 2014). "In the present study, serum PRL level was strongly correlated with adenoma volume." (PMID 25431591, 2014). "Furthermore, maximal adenoma size was larger for patients in the CD + PRL group (mean diameter: 2.44 ± 1.32 cm; range: 0.6–6.0 cm) than for those in the CD group (mean diameter: 1.44 ± 1.05; range: 0.5–4.0 cm) (P < 0.001)." (PMID 25506361, 2014). "This is a case of acromegaly due to a giant, mixed GH- and prolactin-secreting adenoma." (PMID 24166706, 2014). "Additionally, nonfunctioning adenomas demonstrated increased expression of Notch3 compared with functioning adenomas, which included PRL- and GH-secreting adenomas (P=0.026)." (PMID 23426998, 2013). "Notably, the adenomas used in the previous study were larger in size (diameters were >3 cm) and patients presented with markedly elevated serum prolactin levels (>1000 ng/ml), compared with those in our study." (PMID 23426998, 2013). "Accumulating evidence supports the hypothesis that normal and adenoma cells expressing GH, PRL, and TSH are regulated by the pituitary-specific transcription factor-1 (Pit-1) and, therefore, belong to the Pit-1 cell lineage." (PMID 23401791, 2013). "Intracytoplasmic staining for prolactin was observed in 50 – 60% of adenoma cells." (PMID 22011738, 2011).